TMEM272 (transmembrane protein 272)
Synonyms: FLJ37307; LINC00282; NCRNA00282
Gene: Protein-coding gene on chromosome 13 (51,813,347 to 51,845,177, reverse strand). Ensembl gene ENSG00000281106.
Subcellular location: Membrane
Gene Ontology:
Cellular component: membrane
Homologues: Orthologues: macaque TMEM272 (98% identical), pig TMEM272 (78% identical).
Diseases named in the same sentence as TMEM272 in open-access papers:
TMEM272 is named in the same sentence as 4 diseases in open-access papers, as found by Europe PMC text mining. Sharing a sentence is not in itself a finding about the gene and the disease. The quoted sentences say what the papers report.
prostate carcinoma (1 paper, 2020). A carcinoma that arises from epithelial cells of the prostate gland. "We used univariate and multivariate Cox regression analysis to identify seven prognostic signatures for prostate cancer patients, including BCO1, BAIAP2L2, C7, AP000844.2, ASB9, MKI67P1, TMEM272." (PMID 32547947, 2020).
cancer (1 paper, 2020). A tumor composed of atypical neoplastic, often pleomorphic cells that invade other tissues. "AP000844.2, MKI67P1, and TMEM272 were rarely reported in current studies related to cancer, but were classified as risk prognostic genes in this study." (PMID 32547947, 2020).
TMEM272 also shares sentences with these, for which no sentence is quoted: acute lymphoblastic leukemia (1 paper); leukemia (1).